CDH4 (cadherin 4)
Diseases named in the same sentence as CDH4 in open-access papers (continued):
Sharing a sentence is not in itself a finding about the gene and the disease.
cancer (25 papers, 2011 to 2025). A tumor composed of atypical neoplastic, often pleomorphic cells that invade other tissues. "The CDH4 gene, which encodes the R-cadherin protein, has been significantly implicated in the progression and treatment of various cancers." (PMID 40535770, 2025). "The R-cadherin gene has been studied mainly in relation to malignancies, and persistent associations of the risk of cancer have been reported with decreased CDH4 gene expression." (PMID 36362280, 2022). "The CDH4 gene encodes retinal cadherin (R-cadherin), and the deregulation of R-cadherin is implicated in several human cancers." (PMID 36685967, 2022). "Deregulation of CDH4 has been implicated in several human cancers." (PMID 34289835, 2021). "Regarding the Alu polymorphism of the CDH4 gene, the presence of the Yb8NBC516*D allele predominantly in the homozygous state in combinations associated with longevity may indicate an important role of this gene activity in protecting against cancer." (PMID 36362280, 2022). "In recent years, several studies have unveiled the oncogenic or suppressive role of CDH4 in diverse cancer types." (PMID 38402159, 2024). "By analyzing the TCGA database, the results show that CDH4 is more highly expressed in cancer tissue than in normal tissue in HNSCC and OSCC." (PMID 37237299, 2023). "In OSCC, the CDH4 is more highly expressed in cancer tissues than in normal tissues and more highly expressed in cancer tissues than in normal adjacent cancer tissues in the same patient in 32 paired samples." (PMID 37237299, 2023). "The expression of CDH4 is higher in OSCC group than in normal adjacent cancer tissues in 22 paired samples of our OSCC samples." (PMID 37237299, 2023). "The chart shows the differential expression of CDH4 between cancer and normal tissues adjacent to the cancer in the TCGA database." (PMID 37237299, 2023). "After the database sample analysis, we also analyzed the samples of 22 patients' OSCC tissues and normal tissues adjacent to cancer obtained from the First Affiliated Hospital of Fujian Medical University to further clarify the expression of CDH4 in OSCC." (PMID 37237299, 2023). "In contrast to healthy cells with a demethylated promoter, 57–95% of cancer cells have a methylated CDH4 promoter." (PMID 36362280, 2022). "Although there are discrepancies in the functions of CDH4 in human cancers, our study identified and suggested an oncogenic role of CDH4 in PTC." (PMID 34289835, 2021). "Numerous somatic mutations, including cancer-associated mutations in ARID1A, ATM, CDH4, NRAS, and PIK3CA, were shared among the epithelium from the uterine endometrium, endometriotic lesions distant from and adjacent to the carcinoma, and the carcinoma itself." (PMID 33809880, 2021). "The 20q13.33 region overlapped with several cancer related genes such as CDH4, LAMA5, RPS21, KIAA1510, TNFRSF6B (M68, DcR3), RTEL, EEF1A2 and PTK6." (PMID 24165089, 2013). "Our results, together with those of gemcitabine studies, imply the importance of further functional and clinical studies to define the role of the CDH4 gene as a PGx biomarker for the individualization of chemotherapy or as a novel target for cancer drug development." (PMID 40535770, 2025). "However, the expression level and function of CDH4 in different types of cancer remain controversial." (PMID 40535770, 2025). "In another previous study, CDH4 was shown to be a gene that promotes cancer." (PMID 37237299, 2023). "Clinical OSCC samples also confirmed that CDH4 is highly expressed in cancer tissue." (PMID 37237299, 2023). "An analysis of human primary tumors indicated that CDH4 was hypermethylated in colorectal (78%) and gastric (95%) carcinomas, and CDH4 methylation may be an early event in gastrointestinal tumor progression." (PMID 36685967, 2022).
cancer (continued). "Loss of expression of E-cadherin (CDH1), and induction of expression of N- or R-cadherin (CDH2 or CDH4), triggers a series of events that allows cancer cells to become less dependent of their micro-environment, thereby promoting cell migration, invasion and metastasis." (PMID 29164272, 2018). "The cadherin-4 gene (CDH4) of the cadherin family encodes non-epithelial R-cadherin (R-cad); however, the function of this gene in different types of cancer remains controversial." (PMID 27783992, 2016). "Correlations among FAT atypical cadherin 4 (FAT4) expression, cancer immune characteristics, and infiltrated immune cell gene marker sets were analyzed." (PMID 37735184, 2023). "In contrast, certain cadherins, such as R‐cadherin (CDH4) and K‐cadherin (CDH6), can activate oncogenic pathways critical to cancer progression by regulating the activity of downstream effectors." (PMID 32979859, 2020). "After CDH4 knockdown in SACC-83 cells, the percentage of proliferating cells increased, and the degree of differentiation of carcinoma decreased." (PMID 27783992, 2016). "Similarly, seven genes (SGCZ, KANK1, KDM4C, KCNMA1, ZNF263, CDH4, NCAM2) contain partial CNV duplications in both BD‐cancer and BD‐only patients, but the deleted loci are different." (PMID 39140252, 2025). "Previous studies have determined a direct role for the SS18-SSX fusion protein in regulating expression of several cancer-related genes, such as EGR1, FOS, IGF2, FZD10, SOX2, UNCX and CDH4." (PMID 39045458, 2024). "In addition to 33 direct YAP targets (such as BIRC5, CDH4, TEAD1) previously established in epithelial and cancer cells, 1,027 genes were newly identified to be YAP signatures in neutrophils." (PMID 36921037, 2023). "However, our findings demonstrate an overexpression of cytosolic CDH4 rather than membrane-localized CDH4 within PTC tissues, highlighting the versatile role and context-dependent phenotype of CDH4 in human cancers." (PMID 38402159, 2024).
gastrointestinal tumor (4 papers, 2016 to 2023). "These epigenetic changes can also be detected in the patient’s peripheral blood, suggesting that CDH4 gene may play some special roles in the initiation and progression of neoplasms of digestive system." (PMID 27029387, 2016).
neurodegenerative disease (2 papers, 2017 to 2022). A disorder of the central nervous system characterized by gradual and progressive loss of neural tissue and neurologic function. "Lastly, in cases where the present study evidenced down-regulated expression at the protein level (CDH4, MSN, BACE2) the next steps could involve the investigation of murine knock-outs against the background of neurodegenerative disease phenotypes." (PMID 28798667, 2017).
adenocarcinoma (1 paper, 2017). A common cancer characterized by the presence of malignant glandular cells. "In adenocarcinoma, SCLC, other histotypes, and squamous lung cancer, the CDH4 mRNA expression was dropped off." (PMID 28095912, 2017).
colon polyps (1 paper, 2020). "Using the CDH4 gene as a representative marker of 20q13.33, we found that 20q13.33 copy number gain is even more prevalent in colon polyps than in the CRCs (62.6% vs 50.9%, respectively)." (PMID 33087131, 2020). "QPCR of CDH4 copy number revealed that over 60% (124 / 198) of colon polyps demonstrated 20q13.33 amplification." (PMID 33087131, 2020).
digestive system cancer (1 paper, 2022). A primary or metastatic malignant neoplasm involving any part of the digestive system. "In this study, three of these four differentially methylated genes have been reported to be associated with digestive system cancers (USP1, CDH4, and IL1RAP)." (PMID 36685967, 2022).
CDH4 also shares sentences with these, for which no sentence is quoted: Obesity (3 papers); Aphasia (1); autism (1); Autoimmunity (1); bladder urothelial carcinoma (1); cataract (1); cervical cancer (1); cholangiocarcinoma (1); chordoma (1); clear cell renal cell carcinoma (1); colon adenocarcinoma (1); diabetes (1); epidermoid carcinoma (1); epilepsy (1); gastric adenocarcinoma (1); head and neck squamous cell carcinoma (1); hearing loss (1); hepatocellular carcinoma (1); immune deficiency (1); infection (1); leukoplakia (1); lung adenocarcinoma (1); lung squamous cell carcinoma (1); microcephaly (1); Microspherophakia (1); ovarian carcinoma (1); pancreatic ductal adenocarcinoma (1); sinusitis (1); urolithiasis (1); Usher syndrome (1).
A further 2 diseases each share a sentence with CDH4 in 1 paper.